HIF1A (hypoxia inducible factor 1 subunit alpha)
Diseases named in the same sentence as HIF1A in open-access papers (continued):
Sharing a sentence is not in itself a finding about the gene and the disease.
tumor (continued). "Considering the intricate regulation of the immune response by HIF-1α/A2A adenosine receptor signaling pathways, it would be worth investigating HIF-1α and its inhibition in the tumor microenvironment, including T cells, regulatory T cells, and nurse-like cells." (PMID 34572746, 2021). "Therefore, MCT4 seems to be upregulated in GBM under hypoxic conditions via HIF-1α, mainly in the perinecrotic and hyperplastic/microvascular proliferation tumor zones." (PMID 33936203, 2021). "Ultimately, higher tumor expression of HIF-1α correlates with worse clinical outcome." (PMID 34868044, 2021). "To reconcile the divergent role of Hif1α in tumor cell dissemination to bone and lung, we therefore sought to identify factors that may specifically be driving outgrowth of tumor cells in the lung." (PMID 34556788, 2021). "Furthermore, CAIX overexpression in hypoxic conditions also promotes tumor angiogenesis, a protective response mediated by HIF-1α-dependent expression of vascular endothelial growth factor (VEGF) and other epigenetic mechanisms." (PMID 34316328, 2021). "Since the tumor microenvironment is also hypoxic, we speculated that HIF-1α might play an important role in the tumor microenvironment and regulate the invasion and migration of CAFs." (PMID 34631221, 2021). "The HIF-1α-Glut pathway plays an important role in tumor progression." (PMID 32211041, 2020). "To investigate whether digoxin can exhibit an anti-angiogenic effect on tumor cells, we detected the expression of HIF1α in HCT8 cells treated with different concentrations of digoxin by Western blot." (PMID 33442480, 2020). "Overexpression of HIF-1α has been detected in several human tumours." (PMID 32386517, 2020). "Interestingly, L2HGDH (L-2-Hydroxyglutarate Dehydrogenase), a recently characterized epigenetic modulating ccRCC tumor-suppressor with a marked impact on survival, was found to be located only ~ 11.5Mbp from HIF1A on 14q (at 14q21.3)." (PMID 33077781, 2020). "This could be due to an overexpression of HIF-1α induced by C/EBPδ, which allows the survival of tumor cells under hypoxic conditions." (PMID 32560326, 2020). "In the aerobic condition, hydroxylated NAA10 acetylates HIF-1α protein and induces the protein destability, which suggesting that NAA10 mutation may contribute to tumor progression." (PMID 33109235, 2020). "We also previously demonstrated that HIF-1α inhibitor, YC-1 could enhance anti-tumor activity of sorafenib in HCC." (PMID 32670888, 2020). "Notably, HIF-1α induced by the hypoxic tumor microenvironment enhances the expression of adenosinergic molecules, including CD39 and CD73, as well as the adenosine 2B receptor (A2BR)." (PMID 32509584, 2020). "Because the tumor suppressing/promoting role of several immune markers remains controversial to date, we also assessed the potential suppressive role of the immune markers significantly correlated with HIF-1a." (PMID 32825087, 2020). "Therefore, in oncogenic signaling, mTOR directly phosphorylates downstream effectors such as 4E-BP1 and S6K1, which in turn translates HIF1α to improve glycolysis, finally promoting the survival of tumor cells." (PMID 32626538, 2020). "Finally, regarding the mechanism of HIF-1α stabilization, HIF-1α expression was characteristic of well-vascularized tumor in SACs, suggesting a hypoxia-independent mechanism." (PMID 32183342, 2020). "HIF-1α is a major transcription factor that regulates glycolysis in the tumor microenvironment." (PMID 32555715, 2020). "Hypoxia may sustain radioresistance of gliomas, and therefore targeting tumor hypoxia by inhibiting HIF-1α could enhance the radiosensitivity of human malignant gliomas and subsequently improve the radiotherapy outcomes." (PMID 33028364, 2020).
tumor (continued). "The low expression of NDRG1 was accompanied by low protein levels of HIF‐1α and 2α in IHC images of tumour tissues from Patient I. Moderate and high protein levels of HIF‐1α and 2α correspond to moderate and high NDRG1 expression, respectively, from Patients II and III." (PMID 32537867, 2020). "Androgen and HIF1a signaling promoted proliferation in vitro and enhanced tumor growth in vivo." (PMID 32450824, 2020). "Moreover, a set of microRNAs (such as miR-135, miR-421, miR-382, and miR-687), which were abnormally expressed during tumor growth and metastasis, have also been reported to be regulated by HIF-1α." (PMID 32411322, 2020). "These events may occur through the HIF-1α dependent regulation of signaling mediators and inflammatory genes in both cancer and neighboring cells within the tumor microenvironment." (PMID 32778144, 2020). "In cancer, hypoxia has long been recognized as a contributing factor to the development and survival of tumor cells, and HIF-1α has been identified as a key mediator of the adaptive processes which confer a survival advantage in the hypoxic tumor microenvironment." (PMID 32111982, 2020). "Based on the theory that hypoxia promotes tumor progression via activating ROS/HIF-1α signaling axis, we speculate that AAM might exert antitumor effect through eliminating ROS production in a tumor hypoxia microenvironment." (PMID 32499699, 2020). "HIF-1α, as a key transcription factor in tumor cell energy metabolism, activates many genes related to tumor metabolism and glucose transporters, and promotes the proliferation of tumor cells." (PMID 33363466, 2020). "HIF-1α protein was generally upregulated under hypoxia resulting in accelerated tumor growth." (PMID 33292202, 2020). "According to previous investigations and bioinformatics predictions, HIF1A could promote tumour glycolysis, and its promoter region might have a DNA binding motif for TEAD1, a transcription coactivator of YAP1." (PMID 33218358, 2020). "We hypothesized that miR-103a-3p regulates tumour metabolism and biological functions through HIF1A." (PMID 33218358, 2020). "Therefore, CTHRC1 can participate in tumor cell migration and invasion through HIF-1α/CXCR4 signals in GC." (PMID 32848510, 2020). "Tumor HIF-1α, CAIX, Ki67, and PCNA amounts were continuously down-regulated during radiotherapy." (PMID 32766135, 2020). "The expression of NOTCH1, a disintegrin and metalloproteinase 12 (ADAM-12), hypoxia-inducible factor 1 alpha (HIF-1α), and heparin-binding epidermal growth factor (HB-EGF) under hypoxic conditions has been implicated in invadopodia formation, tumour invasiveness, and metastasis." (PMID 32386517, 2020). "An HIF-1α/VEGF-A Axis in cytotoxic T cells was involved in the regulation of tumor progression, while loss of HIF-1α in CD8+ T cells could reduce tumor infiltration and tumor cell killing, and altered tumor vascularization." (PMID 32112550, 2020). "Indeed, in a breast cancer xenograft model, HIF-1α-triggered autophagy in stromal cells is responsible for tumor progression." (PMID 32365852, 2020). "Given the heterogeneity of tumor hypoxia, the expression of HIF-1α and HIF-2α may differ in different tumor areas." (PMID 33251216, 2020). "HSP90 can also be secreted in a variety of tumor cells under the regulation of HIF-1α." (PMID 32766157, 2020). "According to their description, this change could be beneficial for liver function, as HIF-1α governs the transcription of genes controlling proliferation and metastasis of tumor cells." (PMID 32928121, 2020). "Interestingly, a combination of inhibitors of HIF-1α and chemotherapy showed a higher anti-tumor effect than the chemotherapy agent gemcitabine alone." (PMID 33135539, 2020). "Thereafter, the von Hippel Lindau (VHL) tumor suppressor functions as an E3 ubiquitin ligase to mediate the ubiquitination of HIF-1α by specifically binding to these two prolyl-hydroxylated residues, eventually leading to rapid proteasomal degradation of HIF-1α protein." (PMID 32014012, 2020).
tumor (continued). "Moreover, the inhibition of HIF-1α and VEGF expression both at mRNA and protein levels has been reported to suppress tumor growth, whereas targeting mTOR/HIF-1α/VEGF can be considered as a promising strategy in anti-cancer therapy." (PMID 32252351, 2020). "Accordingly, myeloid-specific deletion of Hif1a or Arg1 suppresses tumor growth in mice." (PMID 32396064, 2020). "In vivo, the knockdown of QKI promoted tumor growth and upregulated the expression of HIF-1α." (PMID 32047543, 2020). "HIF-1α also participates in the process of tumor immune responses." (PMID 33245358, 2020). "Interestingly, factors contributing to blood vessel stabilization, such as endostatin derived from collagen XVIII and Pdgfa, were upregulated in HIF-1α-KD tumor cells." (PMID 33142239, 2020). "Growing evidence suggests that the hypoxic conditions inducing the activation of HIF-1α along with immune modulators in the tumor microenviroment disrupt the regulating ability of NK cells, resulting in the exhaustion of the anti-tumor response and poor prognosis." (PMID 32722054, 2020). "Lactate can act as a signalling molecule that activates HIF‐1α and PD‐L1 in tumour cells." (PMID 32851798, 2020). "Validation of several identified mRNA species by real-time qPCR confirmed the downregulation of the proangiogenic Cyr61and Pgts2 as well as the proinflammatory Cox2 and Tnfrsf9 transcripts and the upregulation of a vessel-stabilizing factor Pdgfa in HIF-1α-KD tumor cells." (PMID 33142239, 2020). "Wogonin (flavone), triptolide and EGCG are potent inhibitors of HIF-1α in both tumor cell and EC." (PMID 32012744, 2020). "Among the subunits, HIF1-α is believed to be the one most related to tumor glycolysis." (PMID 32549751, 2020). "Furthermore, our study shows that IQ inhibited the expression of HIF-1α, a key molecule in the regulation of hypoxia, which contributes to the tumor metastasis of OSCC." (PMID 32825464, 2020). "The HIF-1α-PGD-PPP axis inhibits tumor apoptosis mainly through metabolic reprogramming." (PMID 32719331, 2020). "There was a strong immunoexpression of HIF-1α, predominantly in the nucleus of tumour cells." (PMID 33067558, 2020). "Moreover, GBE1 protein levels and HIF1α expression were obviously higher in tumor tissues than they were in the paired peritumor tissues." (PMID 32439898, 2020). "Thus, under normoxic conditions, proline residues 402 and/or 564 are modified by prolyl hydroxylases (PHDs), allowing the recognition of HIF-1α by the Von Hippel–Lindau tumor suppressor that is part of an E3 ubiquitin protein ligase complex." (PMID 33396270, 2020). "Therefore, it is possible that the metabolic phenotype observed in ALDO+RA-treated cells (increased HIF-1α activation, increased aerobic glycolysis, decreased oxidative phosphorylation) is in fact tumour suppressive." (PMID 33148314, 2020). "Whether HIF-1α upregulates FN expression and promotes periFN assembly in the late stage of tumor progression in a pVHL-independent manner warrants further investigation." (PMID 33158289, 2020). "Both HIF1α and HIF2α are known to play an important role in tumor angiogenesis." (PMID 32545251, 2020). "However, under the hypoxic microenviroment of tumor, HIF‐1α subunits are stabilized by coactivator proteins, which enhance them interaction with its binding partner HIF‐1β subunit." (PMID 32533646, 2020). "Interestingly, Sukumar and colleagues have shown that while inhibition of glycolysis (and, in turn, inhibition of HIF-1α expression) led to shortened effector function, it concomitantly enhanced the generation of memory cells and anti-tumor functionality." (PMID 32316260, 2020). "Nuclear and cytoplasmic expression of HIF-1α was detected in tumour cells." (PMID 33123565, 2020). "Additionally, ALDH1A1 promoted tumor angiogenesis via retinoic acid/HIF-1α/VEGF signaling, while being identified as an indication for poor CRC outcome." (PMID 32630086, 2020).
tumor (continued). "The upregulation of HIF-1α is another well-recognized promoter of tumour cell proliferation." (PMID 32806712, 2020). "Additionally, hypoxia-inducible factor-1α (HIF-1α) upregulates PD-L1 in hypoxic tumor microenvironment." (PMID 32489463, 2020). "The carcinogenic role of HIF-1 alpha (HIF1A) may change from the response to proliferation to tumor progression." (PMID 32212787, 2020). "HIF1α is ubiquitously expressed in both tumor and normal tissue." (PMID 32938997, 2020). "Taken together, these results suggest that constitutive HIF-1α activation in dendritic cells–for example, following migration within the hypoxic tumor microenvironment–might impair anti-tumor responses by limiting effector T cell cytotoxicity and function." (PMID 33382742, 2020). "Moreover, we noticed that hypoxic condition extensively existed in HCC, as we observed an elevated expression level of HIF‐1α in liver tumors when comparing to non‐tumor liver tissues." (PMID 32368828, 2020). "In a cancer hypoxic condition, MFGE8 might interact with OS9 and therefore releasing HIF1α, resulting in tumor growth and metastasis." (PMID 32591639, 2020). "Next, we sought to elucidate whether the repressed HIF1α expression played an essential role to mediate the anti-tumor effects of H-1-2." (PMID 32322663, 2020). "HIF‐1a is not only highly expressed in local and metastatic tumours, but also directly related to the differentiation, evolution, invasion, metastasis and prognosis of tumours." (PMID 32596991, 2020). "Furthermore, data demonstrated that the inhibition of PI3K/AKT, Hippo-YAP, activating protein (AP-1), Hedgehog and in particular HIF-1α contributed to reduce angiogenesis of new blood vessels required for tumor growth." (PMID 32331450, 2020). "Mechanisms study showed that the Sal was able of enhancing the chemotherapy effect of Apa through inducing cell apoptosis by increase of pro-apoptotic factors and reprograming the hypoxia tumor-environment by down-regulation of hypoxia-inducible factor (HIF-1α)." (PMID 32397840, 2020). "KLF2 acts as a tumor suppressor in CRC via regulating HIF-1α/Notch-1 signaling pathway." (PMID 32523679, 2020). "Importantly, the endothelial-specific depletion of HIF1α resulted in reduced tumor growth and angiogenesis in experimental Lewis lung carcinoma." (PMID 33614496, 2020). "HIF-1α-KD tumors injected with recombinant Cyr61 showed increased vascular permeability, which is in agreement with Cyr61 as an inducer of aberrant tumor angiogenesis associated with nonfunctional leaky vessels and hypoxia." (PMID 33142239, 2020). "As a target gene of HIF-1α, NDUFA4L2 encodes for a regulatory protein that can block the electron flow from complex I to ubiquinone and is markedly elevated in ccRCC with a prognostic effect on tumor behavior." (PMID 33362855, 2020). "SIRT6, an H3K9 deacetylase, inhibits transcriptional activation of HIF-1α in non-tumor cells and reduces the level of glucose metabolism, but SIRT6 knockdown increased glucose uptake in mice, inhibited mitochondrial respiration, and effectively responded to nutrient deprivation." (PMID 33109235, 2020). "Hypoxia-inducible factor-1 alpha (HIF-1α) is a major regulator of cellular response to changes in oxygen concentration, supporting the adaptation of tumor cells to hypoxia in an oxygen-deficient tumor microenvironment." (PMID 32587480, 2020). "Respectively, levels of HIF-1α were also significantly higher in tumour samples." (PMID 33295886, 2020). "Then, we found that succinate activated the hypoxia‐inducible factor‐1 alpha (HIF‐1α) pathway and induced apoptosis, which could also be up‐regulated by the tumour suppressor lncRNA MEG3." (PMID 31793175, 2020).
tumor (continued). "In addition, they have been shown to reduce a tumor’s ability to adjust to hypoxic conditions via inhibition of the HIF-1α pathway." (PMID 33114525, 2020). "Furthermore, immunohistochemical staining of HIF-1α protein in tumor tissues showed that hypoxia induced factor HIF-1α was significantly decreased in Group IV due to the oxygen pump." (PMID 32266251, 2020). "However, it’s interesting to notice that lower levels of Vit.C advance tumor growth and progression by reducing HIF-1α hydroxylation, thereby stabilizing the HIF-1α levels." (PMID 31947879, 2020). "Areas of overlap between acidosis markers and HIF-1α were also observed in tumor cores." (PMID 33188200, 2020). "We observed downregulation of Cyr61 in HIF-1α-KD tumor cells as well as in tumors." (PMID 33142239, 2020). "Several studies have shown that VEGF and HIF-1α are important for tumor vasculogenesis." (PMID 32322211, 2020). "To gain further insight into in vivo relevant functions of HIF-1α and HIF-2α we compared the molecular features of tumours that developed in the presence of both HIF-1α and HIF-2α to those that were genetically restricted to develop in the absence of either HIF-1α or HIF-2α." (PMID 32807776, 2020). "We indicated a double action of propranolol in the tumour microenvironment by inhibiting the stability of HIF1α, thus mediating decrease of CA IX expression and, at the same time, by its possible effect on CA IX activity by decreasing the activity of protein kinase A (PKA)." (PMID 33228233, 2020). "In summary, CAV1-dependent tumor suppression in the absence of E-cadherin is linked to reduced HIF1α transcriptional activity via diminished NOS-mediated HIF1α S-nitrosylation." (PMID 32825247, 2020). "Tumor samples from surgical resection were processed by HE and HIF-1α staining." (PMID 33110474, 2020). "The characterization of L2HGDH as a tumor suppressor was much more comprehensive than HIF1α." (PMID 33077781, 2020). "Taken together, these findings suggest that a positive feedback loop between MIR210HG and HIF-1α may enhance Warburg effect, which ultimately promotes tumor growth in TNBC." (PMID 33392077, 2020). "In our analysis, all tumor samples tested were HIF-1a positive." (PMID 32903606, 2020). "Finally, we examined the association between HIF‐1α and the key factor in lymphangiogenesis, Prox1, and showed that HIF‐1α+ tumor cells simultaneously expressed Prox1." (PMID 31960509, 2020). "Studies demonstrated that SIRT3 could repress tumor growth by downregulating HIF-1α and decreasing ROS accumulation to regulate the Warburg effect in cancer cells and inhibit tumorigenesis." (PMID 33298860, 2020). "It is a critical regulator of HIF-1α, a master regulator of tumor hypoxia." (PMID 31992226, 2020). "Database prediction has shown that SP1 might be a potential target of HIF-1α's regulation, suggesting the function of HIF-1α in promoting tumor development and metastasis may through the regulation of SP1." (PMID 31892989, 2020). "Previously, it has been shown that HIF-1α is responsible for tumor establishment." (PMID 32509579, 2020). "Transcriptome analysis of sorted MC-38 tumor cells revealed upregulation of vessel-stabilizing factors such as endostatin, Pdgfa, Thbs2 in HIF-1α-KD cells and reduced expression of pro-angiogenic factors such as Cyr61, Cox-2 and Angptl4 when compared to Mock tumors." (PMID 33142239, 2020). "Similarly, the VHL E3 ligase is essential for the ubiquitination and degradation of hypoxia-inducible factor-1 alpha (HIF1a), a TF that regulates many genes necessary for tumor growth." (PMID 32718354, 2020).